PROZ (protein Z, vitamin K dependent plasma glycoprotein)
Description:
Appears to assist hemostasis by binding thrombin and promoting its association with phospholipid vesicles. Inhibits activity of the coagulation protease factor Xa in the presence of SERPINA10, calcium and phospholipids.
Synonyms: PZ
Tractability: Small molecule: it has a binding pocket of medium quality; it belongs to a druggable protein family. Antibody: UniProt places it where antibodies can reach, with medium confidence; UniProt predicts a signal peptide or a membrane-spanning region; its Gene Ontology location is reachable by antibodies, with medium confidence.
Gene: Protein-coding gene on chromosome 13 (113,158,622 to 113,172,387, forward strand). Ensembl gene ENSG00000126231.
Subcellular location: Secreted
Pathways (Reactome):
Metabolism of proteins: Gamma-carboxylation of protein precursors; Removal of aminoterminal propeptides from gamma-carboxylated proteins; Transport of gamma-carboxylated protein precursors from the endoplasmic reticulum to the Golgi apparatus
Hemostasis: Regulation of clotting cascade
Gene Ontology:
Molecular function: protein binding; serine-type endopeptidase activity; calcium ion binding
Biological process: blood coagulation; proteolysis
Cellular component: extracellular exosome; endoplasmic reticulum lumen; extracellular region; Golgi lumen
Genetic constraint (gnomAD): Loss-of-function variants: 40 observed, 27.23 expected, observed/expected ratio (o/e) 1.47, 90% interval 1.14 to 1.86. The upper end of that interval is the gene's LOEUF score, 1.86, which puts it in group 6 of 6, group 1 being the genes least tolerant of losing a copy. Missense variants: 480 observed, 465.71 expected, observed/expected ratio (o/e) 1.03, 90% interval 0.96 to 1.11. Synonymous variants: 181 observed, 188.88 expected, observed/expected ratio (o/e) 0.96, 90% interval 0.85 to 1.08.
Homologues: Orthologues: chimpanzee PROZ (98% identical), macaque PROZ (94% identical), mouse Proz (66% identical), guinea pig PROZ (65% identical), rat Proz (64% identical), tropical clawed frog proz (43% identical), zebrafish proza (34% identical), zebrafish prozb (31% identical), Drosophila melanogaster CG32834 (17% identical), Drosophila melanogaster CG34043 (11% identical). Paralogues in human: PROC (33% identical).
Diseases named in the same sentence as PROZ in open-access papers:
PROZ is named in the same sentence as 30 diseases in open-access papers, as found by Europe PMC text mining. Sharing a sentence is not in itself a finding about the gene and the disease. The quoted sentences say what the papers report.
ovarian carcinoma (4 papers, 2022 to 2023). A malignant neoplasm originating from the surface ovarian epithelium. "Signal intensities for the quantified proteins overall spanned approximately seven orders of magnitude and included several previously reported ovarian cancer marker candidates, such as HE4, MSLN, VCAM-1, CEA, CRP, PROZ, LCAT, and M-CSF." (PMID 36669591, 2023).
deep venous thrombosis (2 papers, 2017 to 2023). "As increased INR is associated with deep venous thrombosis and pulmonary embolus formation, these results suggested that an elevated PROZ level may be associated with the regulation of clotting function in patients with TB." (PMID 28278182, 2017).
hepatocellular carcinoma (2 papers, 2014 to 2022). A malignant tumor that arises from hepatocytes. "In this research, we found that PROZ was a gene related to KDR expression that had significantly low expression in cancer tissue by analyzing the differential genes of cancer tissue and adjacent tissue and the intersection of KDR-related genes in hepatocellular carcinoma." (PMID 36140703, 2022). "The correlation analysis of clinical data showed that the low expression of PROZ was significantly correlated with the poor prognosis of hepatocellular carcinoma, and further studies found that PROZ was closely related to the expression of p-ERK and VEGFR2 in hepatocellular carcinoma." (PMID 36140703, 2022).
hypercoagulable (2 papers, 2017 to 2023). "CD320, RTEL1, UCP2, APOA5 and PROZ participate in healthy-specific or disease-specific subnetworks involving thrombophilia-annotated genes and are related to general thrombophilia mechanisms according to the literature." (PMID 37098010, 2023). "Therefore, the serum levels of SAA in patients cured of TB may be associated with the hypercoagulable state and clotting tendency caused by rifampin-induced DIC whereas the increased level of PROZ may have a role in preventing the formation of this complication." (PMID 28278182, 2017).
eczema (1 paper, 2015). "Novel genes associated with eczema risk were identified (e.g., the PROZ and NEU1 genes)." (PMID 26199674, 2015). "Furthermore, the study identified for the first time that the PROZ and NEU1 genes are potential predictors of eczema." (PMID 26199674, 2015).
ischemic stroke (1 paper, 2009). A stroke disorder caused by obstruction of blood flow to the brain, due to thrombotic (local blood clot formation) or embolic (due to a blood clot or other material traveling from another site) event. "Thus, our results are consistent with the notion that PROZ might be an important factor in the pathogenesis of ischemic stroke in postmenopausal women receiving CEE." (PMID 19402886, 2009).
liver cancer (1 paper, 2022). An epithelial or non-epithelial malignant neoplasm that arises from the liver. "Further, through tissue microarray detection, we found that the expression of PROZ was significantly different in different liver cancer patients." (PMID 36140703, 2022). "The relationship between PROZ and sorafenib resistance was further verified in vitro, and it was found that PROZ regulates the resistance of liver cancer cells to sorafenib by affecting the activity of p-ERK." (PMID 36140703, 2022). "Some studies have shown that PROZ may be severed as a prognostic marker in liver cancer, but the relationship between PROZ and liver cancer is still unclear." (PMID 36140703, 2022).
pancreatic cancer (1 paper, 2022). "PROZ’s relationship with tumors: Recent research has shown that PROZ can be used as a marker of pancreatic cancer through protein identification in the serum." (PMID 36140703, 2022).
pneumonia (1 paper, 2017). An acute, acute and chronic, or chronic inflammation focally or diffusely affecting the lung parenchyma, caused by an infection in one or both of the lungs (by bacteria, viruses, fungi, or mycoplasma.). "ELISA analysis revealed that serum C4BPB, SAA, and PROZ in patients with TB differed significantly from healthy controls, patients with pneumonia or COPD, and treated TB cases." (PMID 28278182, 2017). "In the present study, we established decision tree diagnostic models consisting of SAA, PROZ, and C4BPB to discriminate patients with TB from healthy controls, patients with pneumonia or COPD, and treated TB cases." (PMID 28278182, 2017). "The three new candidate biomarkers SAA, PROZ, and C4BPB were validated by ELISA in 136 patients with TB, 66 healthy controls, 72 patients with pneumonia, and 72 patients with COPD." (PMID 28278182, 2017). "However, few studies are available regarding the serum concentration of PROZ and C4BPB in patients with pneumonia or COPD." (PMID 28278182, 2017).
pulmonary TB (1 paper, 2017). "Therefore, SAA, PROZ, and C4BPB may be suitable as new potential diagnostic biomarkers for pulmonary TB." (PMID 28278182, 2017).
tumor (4 papers, 2014 to 2023). "The previous analysis also showed that PROZ has the highest correlation with the main tumor vascular signals (expression of KDR), and the key to the effectiveness of the combined treatment of HCC with ICIs is to block the VEGF pathway of HCC angiogenesis." (PMID 36140703, 2022). "Tumor size was negatively correlated with the expression of PROZ in our data, which was different from the results of TCGA." (PMID 36140703, 2022). "Our study found that PROZ may be closely related to tumor angiogenesis by analyzing the pathways of genes closely related to PROZ." (PMID 36140703, 2022). "At the same time, our analysis found that PROZ was negatively correlated with genes related to immunotherapy efficacy such as CD8A, CD274 and GZMA, and was also negatively correlated with T-cell infiltration in tumor tissue." (PMID 36140703, 2022).
cancer (3 papers, 2014 to 2022). A tumor composed of atypical neoplastic, often pleomorphic cells that invade other tissues. "The results showed that the expression of PROZ was significantly lower in cancer tissues, while in normal tissues adjacent to the cancer the expression of PROZ was higher." (PMID 36140703, 2022).
cardiovascular disease (2 papers, 2016 to 2022). "Coagulation is an ongoing process in serum and deficiencies of several proteins, such as protein Z (PROZ), fibronectin 1 (FN1), and gelsolin (GSN), have been identified to be involved in cerebrovascular and cardiovascular diseases." (PMID 27379006, 2016).
PROZ also shares sentences with these, for which no sentence is quoted: colon cancer (3 papers); gastric cancer (2); lung carcinoma (2); acute lymphoblastic leukemia (1); adenocarcinoma (1); alcoholic liver diseases (1); breast carcinoma (1); hematological disease (1); lung adenocarcinoma (1); melanoma (1); non-small cell lung carcinoma (1); Nonalcoholic fatty liver disease (1); pulmonary embolus (1); Stroke (1); thrombophilia (1); thyrotoxicosis (1); venous thromboembolism (1).